ANG (angiogenin)
Description:
Secreted ribonuclease that can either promote or restrict cell proliferation of target cells, depending on the context. Endocytosed in target cells via its receptor PLXNB2 and translocates to the cytoplasm or nucleus. Under stress conditions, localizes to the cytoplasm and promotes the assembly of stress granules (SGs): specifically cleaves a subset of tRNAs within anticodon loops to produce tRNA-derived stress-induced fragments (tiRNAs), resulting in translation repression and inhibition of cell proliferation. tiRNas also prevent formation of apoptosome, thereby promoting cell survival (By similarity). Preferentially cleaves RNAs between a pyrimidine and an adenosine residue, suggesting that it cleaves the anticodon loop of tRNA(Ala) (32-UUAGCAU-38) after positions 33 and 36. Cleaves a subset of tRNAs, including tRNA(Ala), tRNA(Glu), tRNA(Gly), tRNA(Lys), tRNA(Val), tRNA(His), tRNA(Asp) and tRNA(Sec). Under growth conditions and in differentiated cells, translocates to the nucleus and stimulates ribosomal RNA (rRNA) transcription, including that containing the initiation site sequences of 45S rRNA, thereby promoting cell growth and proliferation. Angiogenin induces vascularization of normal and malignant tissues via its ability to promote rRNA transcription. Involved in hematopoietic stem and progenitor cell (HSPC) growth and survival by promoting rRNA transcription in growth conditions and inhibiting translation in response to stress, respectively. Mediates the crosstalk between myeloid and intestinal epithelial cells to protect the intestinal epithelial barrier integrity: secreted by myeloid cells and promotes intestinal epithelial cells proliferation and survival. Also mediates osteoclast-endothelial cell crosstalk in growing bone: produced by osteoclasts and protects the neighboring vascular cells against senescence by promoting rRNA transcription (By similarity).
Synonyms: RNASE5; RAA1; HEL168; ALS9; RNASE4
Tractability: Small molecule: a structure with a bound ligand is known. Antibody: UniProt places it where antibodies can reach, with high confidence; its Gene Ontology location is reachable by antibodies, with high confidence; UniProt predicts a signal peptide or a membrane-spanning region. PROTAC: its protein half-life has been measured.
Target class: Enzyme
Gene: Protein-coding gene on chromosome 14 (20,682,950 to 20,698,971, forward strand). Ensembl gene ENSG00000214274.
Subcellular location: Secreted; Nucleus; Nucleus, nucleolus; Cytoplasm, Stress granule
Subcellular location (Human Protein Atlas): Mitotic chromosome; Nucleoli; Nucleoli rim; Actin filaments; Predicted to be secreted
Pathways (Reactome):
Cell-Cell communication: Adherens junctions interactions
Gene expression (Transcription): tRNA-derived small RNA (tsRNA or tRNA-related fragment, tRF) biogenesis
Gene Ontology:
Molecular function: actin binding; copper ion binding; heparin binding; peptide binding; protein binding; protein homodimerization activity; receptor ligand activity; ribosome binding; RNA nuclease activity; signaling receptor binding; tRNA-specific ribonuclease activity; DNA binding; endonuclease activity; RNA endonuclease activity; rRNA binding; nucleic acid binding
Biological process: angiogenesis; cell migration; hematopoietic stem cell proliferation; negative regulation of smooth muscle cell proliferation; negative regulation of translation in response to stress; positive regulation of endothelial cell proliferation; positive regulation of phosphorylation; positive regulation of protein secretion; response to hormone; response to hypoxia; rRNA transcription; signal transduction; signaling; stress granule assembly; actin filament polymerization; antibacterial humoral response; antimicrobial humoral immune response mediated by antimicrobial peptide; cell communication; defense response to Gram-positive bacterium; homeostatic process; innate immune response; negative regulation of apoptotic process; oocyte maturation; ovarian follicle development; placenta development; and 1 more
Cellular component: angiogenin-PRI complex; basement membrane; cytoplasm; cytoplasmic stress granule; endocytic vesicle; extracellular region; nucleolus; nucleus; cytosol; growth cone; neuronal cell body
Genetic constraint (gnomAD): Loss-of-function variants: 0 observed, 1.09 expected, observed/expected ratio (o/e) 0, 90% interval 0 to 1.7. That is too few expected variants to judge how well the gene tolerates losing a copy. Missense variants: 178 observed, 197.91 expected, observed/expected ratio (o/e) 0.9, 90% interval 0.8 to 1.02. Synonymous variants: 74 observed, 77.84 expected, observed/expected ratio (o/e) 0.95, 90% interval 0.79 to 1.15.
Gene-disease validity (ClinGen):
ClinGen rates the evidence that ANG causes each of these diseases.
amyotrophic lateral sclerosis type 9 (autosomal dominant): Limited.
Homologues: Orthologues: chimpanzee ANG (99% identical), macaque ANG (74% identical), mouse Ang (72% identical), rat Ang2 (71% identical), pig ANG (69% identical), mouse Ang2 (65% identical), mouse Ang4 (63% identical), mouse Ang5 (63% identical), mouse Ang6 (56% identical). Paralogues in human: RNASE4 (36% identical), RNASE1 (31% identical), RNASE7 (29% identical), RNASE8 (27% identical), RNASE6 (26% identical), RNASE3 (24% identical), RNASE2 (24% identical), RNASE13 (21% identical), RNASE11 (20% identical), RNASE10 (19% identical), RNASE12 (19% identical), RNASE9 (18% identical).
Diseases named in the same sentence as ANG in open-access papers:
ANG is named in the same sentence as 294 diseases in open-access papers, as found by Europe PMC text mining. Sharing a sentence is not in itself a finding about the gene and the disease. The quoted sentences say what the papers report.
Hypertension (67 papers, 2010 to 2025). The presence of chronic increased pressure in the systemic arterial system. "Hypertension is the major risk factor for thrombotic events and low serum level of anti-thrombotic angiogenin may play an important role in their onset." (PMID 25951297, 2015). "In addition, hypertension was associated with decreased levels of physiological pro-angiogenic mediators such as: angiogenin and bFGF." (PMID 25951297, 2015). "Our findings are coincident to one intervention study promoting the Dietary Approaches to Stop Hypertension (DASH) diet, where AA carriers of the Angiotensinogen genotype (G-6A ANG polymorphism) showed the greatest reduction in DBP." (PMID 33339255, 2020). "Another study reported that serum ANG levels were higher in pregnancies complicated by hypertension than in normal, healthy pregnancies." (PMID 32075190, 2020). "A study reported that serum ANG levels were lower in normal pregnancies than those in pregnancies complicated by hypertension." (PMID 29736193, 2018). "Patients with hypertension had significantly lower serum levels of angiogenin and bFGF than normotensive controls (p = 0.01 for both)." (PMID 25951297, 2015). "As it was mentioned before, patients with hypertension were characterized by lower serum levels of angiogenin." (PMID 25951297, 2015). "Therefore, bearing in mind all mentioned properties of angiogenin, our observations shed new light on the pathogenesis of hypertension and development of its complications." (PMID 25951297, 2015). "Previously, angiogenin was only measured in pregnancy induced hypertension and hypertensive patients with heart failure, while there were no data regarding its serum levels in arterial hypertension without cardiac complications as we present in the current study." (PMID 25951297, 2015). "In addition, 17 proteins in the sera of HFPEF patients were significantly increased than that in patients with hypertension, while angiogenin was the only one that was increased by more than five times." (PMID 25124701, 2014). "We hypothesized that RAS gene SNPs that were associated with hypertension and/or decreased efficacy of ACEIs or ARBs as a result of activated RAS, including AT1R rs5186, AT2R rs11091046, REN rs12750834, ANG rs4762, and ANG rs699, could predispose to a higher risk ofnon-invasive BC." (PMID 34898568, 2021). "In addition, we found no impact of the HFPEF risk factors (including sex, hypertension, diabetes mellitus and atrial fibrillation) on angiogenin expression, which was in accordance with the results of antibody microarrays analyses." (PMID 25124701, 2014). "We found that genes related to hypertension—such as ACE, ANG, CAD, BMPR2, and other genes—were also significantly expressed in ascending aortic dissection tissue reported in the literature." (PMID 34262602, 2021). "Therefore, decreased level of angiogenin in hypertension may have severe clinical consequences." (PMID 25951297, 2015).
amyotrophic lateral sclerosis (42 papers, 2007 to 2025). Amyotrophic lateral sclerosis (ALS) is a neurodegenerative disease characterized by progressive muscular paralysis reflecting degeneration of motor neurons in the primary motor cortex, corticospinal tracts, brainstem and spinal cord. "Ivanov and Anderson reported that the Angiogenin-associated G-quadruplex structures also promote motor neuron recovery under apoptotic conditions, revealing a potential mechanism for Amyotrophic Lateral Sclerosis (ALS)." (PMID 32890397, 2020). "0.5–1% of ALS (Amyotrophic Lateral Sclerosis) and Parkinson's disease (PD) are associated with mutations in the angiogenin (ANG)." (PMID 32111867, 2020). "A high expression of angiogenin has been described in different types of cancer, and mutations in the angiogenin gene have been characterized in amyotrophic lateral sclerosis and Parkinson's disease." (PMID 30008694, 2018). "In 2004, hRNase5/ANG was identified for the first time as one of the key genes associated with amyotrophic lateral sclerosis (ALS), a common neurodegenerative disease that affects nerve cells in the brain and the spinal cord." (PMID 30449278, 2018). "We now show that tRNAs lacking cytosine-5 methylation are prone to be cleaved by angiogenin, and altered tRNA cleavage due to mutations in angiogenin is also linked to neurodegenerative diseases, such as amyotrophic lateral sclerosis and Parkinson's." (PMID 25063673, 2014). "The Angiogenin (ANG) gene is frequently mutated in patients suffering from the neurodegenerative disease - amyotrophic lateral sclerosis (ALS)." (PMID 25372031, 2014). "The potent angiogenic factor, angiogenin, has recently been associated with neurodegenerative diseases, such as Amyotrophic Lateral Sclerosis (ALS) and Parkinson Disease (PD)." (PMID 23409128, 2013). "Mutations in the coding region of angiogenin (ANG) gene have been found in patients suffering from Amyotrophic Lateral Sclerosis (ALS)." (PMID 22384259, 2012). "Missense mutations in angiogenin are associated with amyotrophic lateral sclerosis." (PMID 27077847, 2016). "Mutations in tRNA cleavage enzymes (ANG) have been reported in Amyotrophic Lateral Sclerosis (ALS) and PD." (PMID 40216606, 2025). "Nevertheless, some ANG variants are involved in both neurodegenerative Parkinson disease (PD) and Amyotrophic Lateral Sclerosis (ALS)." (PMID 34576228, 2021). "A study on 3146 PD patients and 7668 controls demonstrated a high prevalence of ANG variants in PD and amyotrophic lateral sclerosis (ALS), showing a possible link between the tRNA processing enzyme –ANG with PD and ALS." (PMID 32899928, 2020). "Mutations in the ANG gene have been characterized in amyotrophic lateral sclerosis (ALS) and Parkinson’s disease (PD)." (PMID 31500197, 2019). "ANG mutants show reduced ribonuclease (RNase) activity and were first implicated in the pathogenesis of amyotrophic lateral sclerosis (ALS)." (PMID 31080456, 2019). "Mutations in ANG are associated with neurodegenerative diseases such as Amyotrophic Lateral Sclerosis (ALS) and Fronto-temporal dementia (FTD)." (PMID 29486010, 2018). "Mutations in the angiogenic factor, angiogenin (ANG), have been identified in patients with both familial and sporadic amyotrophic lateral sclerosis (ALS) and are thought to have a neuroprotective function." (PMID 25386690, 2014). "The potent angiogenic factor, angiogenin (ANG), has been known to associate with both familial and sporadic Amyotrophic Lateral Sclerosis (ALS)." (PMID 25386690, 2014). "The angiogenic factor, angiogenin, has been recently linked to both Amyotrophic Lateral Sclerosis (ALS) and Parkinson Disease (PD)." (PMID 23409128, 2013). "We have shown previously that mutations in ANG are associated with amyotrophic lateral sclerosis (ALS), and that ANG mutations predict loss of RNAse and angiogenic function." (PMID 21085671, 2010).
amyotrophic lateral sclerosis (continued). "Research related to amyotrophic lateral sclerosis revealed that angiogenin plays an important role in the endogenous protective pathways of motor neurons exposed to hypoxia." (PMID 35052815, 2022). "Importantly, mutations affecting ANG ability to be translocated into the nucleus have been detected in various cohorts of amyotrophic lateral sclerosis (ALS) and/or Parkinson’s disease (PD) patients." (PMID 34576228, 2021). "Given the established roles of ANG in the etiology of disorders such as cancer, infection, and rare diseases, such as amyotrophic lateral sclerosis, further investigations of the molecular mechanisms mediated by ANG are required." (PMID 34356982, 2021). "Mutations in angiogenin are linked to the development of amyotrophic lateral sclerosis (ALS)." (PMID 32927693, 2020). "More specifically, Angiogenin seems to be involved in the development of amyotrophic lateral sclerosis and Parkinson’s disease." (PMID 29467462, 2018). "Angiogenin (ANG), a peculiar member of the RNase A superfamily, is a potent inducer of angiogenesis involved in many different types of cancer, amyotrophic lateral sclerosis and also with a possible role in the innate immune defense." (PMID 17883850, 2007). "Therefore, we studied here the self-association propensity of ANG and of three of its pathogenic variants found in amyotrophic lateral sclerosis (ALS) and Parkinson’s Disease (PD) patients, namely H13A-ANG, S28N-ANG, and R121C-ANG." (PMID 34576228, 2021). "Through these case studies, the construction and analyses of a PPI network for angiogenin protein in amyotrophic lateral sclerosis, a signal-gene-protein interaction network for presenilin protein in Alzheimer's disease and a Boolean network for a mammalian cell cycle was demonstrated." (PMID 23286825, 2013). "The absence of this feature in the present case indicates that patients with ANG mutations do not always have pathological changes distinguishable from those of sporadic amyotrophic lateral sclerosis." (PMID 23228179, 2013). "Too little h-ANG activity leads to abnormal protein oligomerization, resulting in Amyotrophic Lateral Sclerosis (ALS) or Parkinson’s disease." (PMID 33535464, 2021). "Mutations in the angiogenin (ANG) gene are known to be associated with both familial and sporadic amyotrophic lateral sclerosis (ALS)." (PMID 31025543, 2019). "In terms of diseases, many different ANG gene mutations have been identified in patients with amyotrophic lateral sclerosis (ALS) and Parkinson’s disease, implying that ANG-catalyzed production of tRNA halves could be involved in the pathogenesis of these neurodegenerative disorders." (PMID 30538719, 2018). "Mutations in Angiogenin (ANG), a member of the Ribonuclease A superfamily (also known as RNase 5) are known to be associated with Amyotrophic Lateral Sclerosis (ALS, motor neurone disease) (sporadic and familial) and Parkinson’s Disease (PD)." (PMID 28176817, 2017). "ANGDelMut is a web-based tool for predicting the functional consequences of missense mutations in the angiogenin (ANG) protein, which is associated with amyotrophic lateral sclerosis (ALS)." (PMID 24555108, 2013).
COVID-19 (33 papers, 2020 to 2025). A disease caused by infection with severe acute respiratory syndrome coronavirus 2. "Additionally, 13 of 55 angiogenic proteins including TIMP-1, uPA, VEGF, MMP-8/9, CXCL4/16, Endoglin, Angiogenin or Angiopoietin-2 were uniquely downregulated in 3-months post-COVID-19 patients without PE compared to those who suffered a PE." (PMID 38324145, 2024).
diabetes (33 papers, 2012 to 2025). "Some studies investigated the associations between serum angiogenin levels in type 1 diabetes mellitus." (PMID 39273664, 2024). "CKD is an established risk factor for CVD in patients with diabetes, and a cross-sectional study among 108 participants revealed that plasma angiogenin increases with advanced CKD stages." (PMID 38360721, 2024). "We also explored whether plasma angiogenin might improve the prediction ability of MACE above the European Heart Association SCORE2-Diabetes." (PMID 38360721, 2024). "There were 8 studies reported on the association between diabetes and serum ANG levels." (PMID 29736193, 2018). "Diabetes is strongly associated with both microvascular and macrovascular diseases; thus, its pathogenesis may be related to the abnormal expression of proangiogenic factors, such as ANG." (PMID 29736193, 2018). "In our study, we only observed a modest positive correlation between plasma angiogenin levels and diabetes duration, mean arterial pressure, triglyceride and an inverse correlation with HDL-cholesterol and kidney function." (PMID 38360721, 2024). "Plasma angiogenin significantly correlated positively with diabetes duration, mean arterial pressure, triacylglycerol, urine ACR, high sensitivity c-reactive proteins (hs-CRP) and inversely with HDL-cholesterol and eGFR." (PMID 38360721, 2024). "The findings of our study indicated that the levels of angiogenin were also notably elevated in young patients with diabetes when compared to the control group." (PMID 39273664, 2024). "When comparing patients with diabetes to controls, they found that angiogenin concentrations were significantly lower in patients with type 2 diabetes." (PMID 37761032, 2023). "Based on these data, we all but confirmed that USCs secreted exosomes carrying some BMP-7 and high levels of VEGF, TGF-β and angiogenin to be involved in renal protection in diabetes." (PMID 26852014, 2016). "However, the angiogenin level was found to be statistically significantly higher in the group of patients with both diabetes and Hashimoto’s disease." (PMID 39273664, 2024). "Our finding may pave the avenue for future preclinical and clinical studies to further characterize the role of angiogenin in the pathological pathway leading to cardiovascular disease in individuals with diabetes." (PMID 38360721, 2024). "Angiogenin, among other factors, contributes to vascular complications in diabetes." (PMID 37761032, 2023). "Reduced serum angiogenin levels in patients with diabetes may be responsible for impaired angiogenesis, especially in those with long-standing disease." (PMID 37761032, 2023). "The presented analysis of the levels of selected cytokines in patients with diabetes mellitus, with and without Hashimoto’s disease, revealed that only angiogenin levels were significantly elevated in the group with Hashimoto’s disease." (PMID 39273664, 2024). "Adding plasma angiogenin to predictors in the SCORE2-Diabetes score did not significantly improve the C-index (AUC 0.698 to 0.701, delta 0.003, 95% CI -0.015-0.022)." (PMID 38360721, 2024).